SSB (small RNA binding exonuclease protection factor La)
Diseases named in the same sentence as SSB in open-access papers (continued):
Sharing a sentence is not in itself a finding about the gene and the disease.
lupus (continued). "Neonatal lupus and neonatal heart disease do not appear to be significantly associated with the new-onset lupus during pregnancy or LN pregnancies, which may be associated with the anti-Ro/SSA and anti-La/SSB and needs further investigation." (PMID 27442513, 2016). "Some researchers suggest that anti-Ro60 abs are sufficient to diagnose pSS, while anti-La/SSB abs are heterogenous and may be present in other autoimmune diseases, such as systemic lupus erythematosus (SLE), neonatal lupus erythematosus (NLE), and inflammatory myositis as well as pSS." (PMID 39364411, 2024). "Previously we found that salivary anti-SSB/La level was significantly higher in primary SS patients compared with systemic lupus erythematosus (SLE) and healthy control individuals." (PMID 24489858, 2014). "Immune-mediated congenital heart block (CHB) is a rare but severe manifestation of neonatal lupus, resulting from transplacental transfer of maternal anti-SSA/Ro and anti-SSB/La antibodies." (PMID 41918634, 2026). "Lupus anticoagulant, anti-cardiolipin antibodies, anti-β2-glycoprotein I antibodies, anti-SSA and anti-SSB antibodies." (PMID 37781682, 2023). "While anti-SSA can also be found in other CTDs such as systemic lupus erythematosus (SLE), anti-SSB is more specific for Sjögren’s syndrome." (PMID 31298300, 2020). "Another spectrum is neonatal lupus with cardiac and cutaneous anomalies in newbornsof mothers with anti-Ro/SSA and anti-La/SSB autoantibodies." (PMID 30202131, 2018). "Antinuclear antibodies and anti-Ro/SSA and anti-La/SSB antibodies were negative in both the neonate and the mother, reducing the likelihood of neonatal lupus." (PMID 40357088, 2025). "In addition, autoantibodies that are common to both lupus and SD, specifically anti-SSA (Ro), anti-SSB (La), and anti-RNA, were diminished in the double-knockout mice as compared to Tlr8-deficient animals." (PMID 39310226, 2024). "Other antibodies were largely unremarkable (DS-DNA antibody, anti-RNP, anti-Smith, Scleroderma antibody, SSA/SSB antibody, Jo-1 antibody, RF, pANCA, cANCA, anti-LKM, anti-Smooth muscle, anti-mitochondrial) leading to a likely diagnosis of systemic lupus erythematosus (SLE) flare." (PMID 38813330, 2024). "This is because antibodies to SSA and SSB are not specific to SjS, but are also found in other rheumatological diseases including systemic lupus erythematosus (SLE), and myositis." (PMID 19778440, 2009). "Furthermore, 47 (23.7%) pregnancy episodes developed in women who were anti-Ro/SSA or anti-La/SSB positive, and none of the newborns had neonatal lupus or CHB." (PMID 33916674, 2021). "The mothers of these children often have an autoimmune disorder (i.e. systemic lupus erythematosus [SLE] and/or Sjögren's syndrome [SS]), with antibodies against SSA/Ro and/or SSB/La antigens." (PMID 16356190, 2006).
autoimmune disease (53 papers, 2008 to 2026). A disorder resulting from loss of function or tissue destruction of an organ or multiple organs, arising from humoral or cellular immune responses of the individual to their own tissue constituents. "Maternal autoimmune diseases, with anti‐ssA (Ro) and anti‐ssB (La) antibodies implicated in 56%–90% of cases, are primary causes." (PMID 41567826, 2026). "More challenging is the fact that although anti-Ro/SSA and anti-La/SSB are hallmark serological antibodies for pSS, they can also be found in other autoimmune diseases, such as systemic lupus erythematosus, and even in some healthy individuals." (PMID 41438427, 2026). "Sjogren’s syndrome antigen B (SSB) is an autoantigen associated with autoimmune disorders." (PMID 24489858, 2014). "This form is characterized by the absence of anatomical malformations in the heart, accompanied by maternal autoimmune disease and/or autoantibody positivity, particularly anti‐ssA (Ro) and anti‐ssB (La) antibodies." (PMID 41567826, 2026). "Primary Sjogren’s syndrome (pSS) is an autoimmune disease that is difficult to clinically diagnose; to diagnose pSS, serum SS-A/Ro and SSB/La antibodies are assessed clinically." (PMID 40217840, 2025). "Salivary Anti-Ro/SSA and Anti-La/SSB antibodies are essential for the diagnosis ofSjogren's syndrome, an autoimmune disease that affects exocrine glands." (PMID 40230914, 2024). "In contrast, anti-SSB/La are typically found only in patients affected by SS, and if they are detected among patients with other autoimmune disorders, anti-SSB/La antibodies are always accompanied by anti-SSA/Ro antibodies." (PMID 34115263, 2022). "Autoimmune congenital heart block (CHB) is part of Neonatal Lupus Syndrome and is a model of passively acquired autoimmunity disease, caused by transplacental passage of circulating anti-Ro/SSA and anti-La/SSB autoantibodies to fetal conduction cardiac tissue." (PMID 33415090, 2020). "Congenital heart block (CHB) is a transplacentally acquired autoimmune disease associated with anti-Ro/SSA and anti-La/SSB maternal autoantibodies and is characterized primarily by atrioventricular (AV) block of the fetal heart." (PMID 24039792, 2013). "Congenital heart block (CHB) is a passively acquired autoimmune disease that occurs in pregnancies of rheumatic mothers, but also in healthy mothers, and has been associated with maternal anti-Ro/SSA and anti-La/SSB antibodies." (PMID 24039792, 2013). "Since B19-NS1 has been known to induce apoptosis and linked to the pathogenesis of autoimmune disorders, herein we further examined the presence of various autoantigens, including Sm, U1-snRNP, SSA, SSB, Scl-70, Jo-1, Ku, CENP-A/B." (PMID 20500824, 2010). "One of the first-described antibodies associated with autoimmune diseases was antinuclear antibodies, and then SSA and SSB antibodies were found, especially in SS." (PMID 18419828, 2008). "This disease is usually associated with the production of specific antibodies, such as anti-Ro/SSA and anti-La/SSB, and can occur independently or in combination with other autoimmune diseases, such as rheumatoid arthritis, septic shock, or autoimmune liver disease." (PMID 39519619, 2024). "Anti-SSA/Ro and anti-SSB/La antibodies have been reported to be elevated in sera of patients with autoimmune diseases upon exposure to intracellular autoantigens, which are discharged into the microenvironment through secretion of autoantigen-containing exosomes or by cell death." (PMID 30347705, 2018). "Whether the early upregulation of La/SSB autoantibodies in humans has specificity for later development of SLE or other autoimmune disorders remains undetermined." (PMID 22838636, 2012). "Indeed, various apoptotic cell antigens, including fragmented endoplasmic reticulum, ribosomes, ribonucleoprotein, nucleosomal DNA, SSA/Ro, SSB/La, and small nuclear ribonucleoproteins, have been recognized as targets of autoantibodies across a broad spectrum of autoimmune diseases." (PMID 20500824, 2010).
autoimmune disease (continued). "Detailed laboratory tests for autoimmune diseases confirmed positivity for anti-Jo1, anti-Sm, and anti-SSA/Ro antibodies, along with clinically relevant titers of anti-CENP-B, anti-SSB/La, and anti-histone antibodies." (PMID 41399591, 2025). "Mothers with autoimmune diseases, especially those positive for anti-SSA/Ro and anti-SSB/La antibody antibodies, should receive counselling about CHB risk during prenatal care." (PMID 40066690, 2025). "Autoimmune diseases, such as SLE, are characterized by circulating autoantibodies that recognize double‐stranded (ds) DNA, nuclear proteins [such as SSA (Ro‐52) and SSB (La)], and mitochondrial cardiolipin." (PMID 30498131, 2019). "The first-line screening tests for these autoimmune disorders include ANA and anti-extractable nuclear antigen antibodies (ENA) (anti-Ro/SSA, anti-La/SSB, anti-Sm, anti-RNP, anti-Jo1, anti-Scl-70 (anti-topoisomerase I), and anti-centromere (CENP-B) antibodies)." (PMID 41602963, 2026). "Notably, neonatal lupus is the most significant fetal complication of maternal autoimmune diseases, particularly when SSA/SSB antibodies are positive." (PMID 40821243, 2025). "In autoimmune diseases such as SjD, SLE, RA, and systemic sclerosis (SSc), Ro60 autoantibodies often co-exist with autoantibodies targeting Ro52 (also called TRIM21) and La/SSB." (PMID 39062948, 2024). "Moreover, other causes of these symptoms should be excluded via detailed inquiry regarding the maternal history of autoimmune diseases and timely autoantibody testing, particularly anti-SSA/SSB antibodies." (PMID 38360914, 2024). "SS is a B-cell mediated autoimmune disease with anti-SSA (Ro), anti-SSB, and ANA Abs." (PMID 37781409, 2023). "In light of the specific value of serological characteristics in diagnosing autoimmune diseases, the pSS patients with positive scores expressed a preference for autoantibodies to SSA and SSB and obviously higher levels of RF, IgG and γ-globulin% (p < 0.05, overall)." (PMID 34930431, 2021). "It needs to be clarified that the patients with other autoimmune diseases such as rheumatoid arthritis, which may show SSA/SSB, ANA, or RF positive, have been excluded in the patient group." (PMID 31886299, 2019). "Primary Sjögren’s syndrome is an autoimmune disease with inflammatory infiltration, with mononuclear cells affecting primarily the exocrine glands, epithelium damage, and hyperreactivity of B cells with autoantibodies against ribonucleoproteins: anti-SSA/Ro and anti-SSB/La production." (PMID 36148238, 2022). "Therefore, when newborns present with multiple organ involvement resembling NLE, they should be carefully evaluated, particularly for NLE, even if their mothers have no relevant history of autoimmune diseases or are negative for autoantibodies such as anti-SSA/SSB antibodies." (PMID 38360914, 2024). "None of the patients had evidence of other autoimmune disease such as positive ANA, anti dsDNA, rheumatoid factor, or anti SSA/SSB antibodies." (PMID 26754737, 2016). "This case involves a patient with no clear history of autoimmune diseases but multiple immunological abnormalities, including ANA (speckled pattern 1:1000), positive anti-SSA and anti-SSB antibodies, transient low-titer ACL-IgM, and a one-time high-titer anti-β2-GP1 positivity." (PMID 41451211, 2025). "Thus, both TROVE2 and SSB transcripts and Ro60 and La proteins were profoundly diminished in RRMS and these mRNA and protein expression differences were not seen in several other autoimmune diseases." (PMID 25885816, 2015).
dry eyes (28 papers, 2010 to 2025). "We conclude that dry mouth, dry eye, anti-Ro52 positive, anti-SSB positivity, and RF positivity are risk factors for SLE progressing to SLE-SS." (PMID 36675463, 2023). "We found that 2% of patients presented with DES exhibited a combination of anti-SSA/Ro and anti-SSB/La autoantibodies, which form part of the diagnostic criteria for SS, in addition to their signs and symptoms of dry eyes." (PMID 33382786, 2020). "Key findings include positive anti-Ro/SSA and anti-La/SSB antibodies, along with keratoconjunctivitis sicca and xerostomia." (PMID 40002713, 2025). "The five best characteristics were selected by LASSO logistic regression in the discovery cohort of SLE versus SLE-SS and were used to construct the predictive tool, including dry mouth, dry eye, anti-Ro52 positive, anti-SSB positive, and RF positive." (PMID 36675463, 2023). "Additionally, increased levels of anti-Ro/SSA and anti-La/SSB autoantibodies have been detected in the tears of SjD patients, with their presence correlating with the severity of dry eye symptoms." (PMID 40852371, 2025). "Therefore, we should be aware of the development of combined SS when young SLE patients present with dry mouth, dry eye, or positive anti-Ro52, anti-SSB, or RF." (PMID 36675463, 2023). "A diagnosis of pSS can be made by quantifying the degree of xerostomia/xerophthalmia, a special stain for the eyes, from histologic findings of minor salivary glands, and the presence of pSS-associated autoantibodies such as anti-Ro/SSA and anti-La/SSB." (PMID 34731207, 2021). "They found that FS >1 was significantly associated with serum anti-SSA and anti-SSB positivity, RF, but not with symptoms of dry mouth and/or dry eyes." (PMID 34177936, 2021). "Here, we report the case of a patient who presented with xerostomia and xerophthalmia accompanied by positive ANA, anti-SSA, and anti-SSB titers in the blood." (PMID 39055718, 2024). "She had been diagnosed as having pSS 16 years previously, based on the objectively confirmed presence of dry eyes, dry mouth and positivity for anti-Ro/SSA and anti-La/SSB antibodies." (PMID 31842799, 2019). "In summary, in SLE patients with negative anti-SSA/SSB, dry eye severity was strongly correlated with anti-dsDNA and C3 but not with C4, ESR, and ANA." (PMID 27428227, 2016). "As anti-dsDNA is highly specific for SLE and is highly correlated with dry eye severity, our findings have established a strong evidence of association between dry eye severity and SLE patients with negative anti-SSA/SSB." (PMID 27428227, 2016). "All patients were negative for anti-Ro/SSA and anti-La/SSB antibodies, and none of them had Keratoconjunctivitis sicca symptoms or positive responses to subjective symptoms related to Sjögren ́s syndrome (dryness feeling in eyes, lip and the nose - questions 9, 10 and 11 of xerostomia Inventory)." (PMID 26595829, 2016). "Due to the increased evidences that dry eye syndrome in SLE patients may not be as much associated with sSS, we investigated the SLE patients who were anti-SSA/SSB negative without any oral symptoms to rule out sSS." (PMID 27428227, 2016). "Besides, the reason why the thiol/disulphide balance did not change with anti-SSA or anti-SSB positivity, salivary gland biopsy results, xerostomia, or xerophthalmia may have been ascribed to medication use as well." (PMID 34177371, 2021). "Furthermore, we questioned the patient's past medical history, no common symptoms, such as dry mouth or dry eyes, while the SS-related diagnoses were positive, including ANA, anti-SSA antibody, anti-SSB antibody, anti-Ro-52 antibody, Sch-I test, TBUT, and labial gland biopsy." (PMID 33157952, 2020).
neonatal lupus (23 papers, 2011 to 2026). "Neonatal lupus erythematosus (NLE) is a rare acquired autoimmune disease associated with the entry of maternal anti-Ro/SSA and anti-La/SSB antibodies into fetal circulation via the placenta." (PMID 39228436, 2024). "Neonatal lupus is associated with the transfer of anti-SSA/Ro and anti-SSB/La antibodies across the placenta." (PMID 38791261, 2024). "Antibodies against Ro/SSA and La/SSB are detected frequently and have been associated with SCLE and neonatal lupus erythematosus (NLE), in addition to SLE and Sjogren's Syndrome." (PMID 32714331, 2020). "Neonatal lupus erythematosus (NLE) is a rare autoimmune condition caused by the transplacental transfer of maternal IgG autoantibodies, most commonly anti-Sjögren's-syndrome-related antigen A (anti-Ro/SSA) and anti-Sjögren's-syndrome-related antigen B (anti-La/SSB)." (PMID 41694992, 2026). "Neonatal lupus is a rare syndrome, which occurs in 1% to 2% of NBs to mothers with anti-SSA and/or anti-SSB autoantibodies, manifesting more frequently by cardiac, cutaneous, hematological, and hepatic alterations." (PMID 37944923, 2023). "Neonatal lupus is the description used to describe infants who are affected by maternally derived antibodies (anti-Ro/SSA and anti-La/SSB)." (PMID 33158209, 2020). "Neonatal lupus is a consequence of trans-placental migration of maternal immunoglobulin G (IgG) autoantibodies to SSA and/or SSB autoantigens." (PMID 33178534, 2020). "Among the five patients born to mothers positive for anti-SSA and anti-SSB antibodies, there were no cutaneous manifestations of neonatal lupus syndrome (NLS), hepatosplenomegaly, or abnormal liver function tests." (PMID 40492165, 2025). "Neonatal lupus erythematosus (NLE) is a rare autoimmune disorder characterized by cutaneous and/or cardiac manifestations resulting from the transplacental passage of maternal antibodies, including anti-SSA/Ro, anti-SSB/La, and occasionally anti-U1RNP." (PMID 40098636, 2025). "Neonatal lupus as a disease entity occurs due to passively-acquired autoimmunity, in which tissue injury in the fetus results from the transplacental transfer of maternal IgG autoantibodies to SSA/Ro and SSB/La intracellular proteins." (PMID 37346216, 2023). "Neonatal lupus erythematosus (NLE) is a rare immune-mediated disease characterized by the transplacental passage from the mother to the fetus of autoantibodies, in particular SSA or SSB or both." (PMID 20864789, 2011). "Neonatal lupus erythematosus (NLE) is a spectrum of cutaneous, cardiac, and systemic manifestations seen in a neonate born to a mother with autoantibodies against Ro/Sjögren's-syndrome-related antigen A (SSA) and La/Sjögren's-syndrome-related antigen B (SSB)." (PMID 39171053, 2024).
Autoimmunity (21 papers, 2006 to 2026). The occurrence of an immune reaction against the organism's own cells or tissues. "Nascent, precursor tRNAs (pre-tRNAs) are bound by the Lupus autoantigen La, a protein first identified in RNPs targeted by autoimmune antibodies (also referred to as Sjogren syndrome antigen B, SSB; Yoo & Wolin, 1997)." (PMID 36754845, 2023). "Diagnosis requires serological (presence of SSA/Ro or SSB/La) or histological (minor salivary gland biopsy) evidence of autoimmunity." (PMID 31126347, 2019). "Damaged epithelial cells release autoantigens, especially Ro/SSA and La/SSB, which create autoimmunity and autoantibodies secretions." (PMID 24985362, 2015). "The diagnosis can be made if there are objective findings of ocular and/or oral dryness with the presence of underlying autoimmunity (with a positive anti-SSA in the presence or absence of anti-SSB) and a positive biopsy showing lymphocytic infiltration." (PMID 39749076, 2024). "Although the authors did not focus on the group of normocomplementemic SLE, they found that the aPL-group tended to have stronger signs of autoimmunity and complement activation, whilst the SSA/SSB+ subgroup was marked by higher IFN inflammation." (PMID 32334613, 2020). "In order to rule out other autoimmune conditions, a comprehensive ANA panel was conducted (including Hep2, dsDNA, ssDNA, Sm, Rnp/Sm, ssa-Ro60m, SSB-La, and Scl-7), with all results within normal limits." (PMID 39202320, 2024). "Among all the antibodies with differences, 12 IgG antibodies against Jo-1, SSB, PL-12, PM/scl100, Scl-70, TIF1γ, β-actin, MPO, TTG, AQP4, calprotectin, and CRP were more abundant in patients with autoimmunity than in those without (p < 0.05)." (PMID 38634985, 2024).